ULBP2 (UL16 binding protein 2)
Diseases named in the same sentence as ULBP2 in open-access papers (continued):
Sharing a sentence is not in itself a finding about the gene and the disease.
infection (16 papers, 2011 to 2025). The state of being infected such as from the introduction of a foreign agent such as serum, vaccine, antigenic substance or organism. "Infection with the ULBP2-expressing HCMV strain caused diminished cell surface levels of MHC class I molecules." (PMID 27907183, 2016). "ULBP2 expression was reduced at 24 hrs post-infection, and ULBP3 expression was reduced as early as 12 hrs post-infection." (PMID 37753084, 2023). "In agreement with the FACS results, infection of A549 with HMPV/WT significantly decreases the ULBP2 protein level." (PMID 32698530, 2020). "Since MICA, MICB, and ULBP2 surface levels were significantly higher in cells infected with ΔRh159 compared to RhCMV, we wanted to specifically address the impact of Rh159 on the maturation of these NKG2DLs when newly synthesized during infection." (PMID 27580123, 2016). "However, spread of the ULBP2 expressing strain was markedly more inhibited leading to less infected cells per focus of infection as well as a lower number of infectious foci in cell cultures." (PMID 27907183, 2016). "We set out to determine whether the rapid up regulation of NKG2DL transcription driven by expression of the major HCMV IE genes would result in transient exposure of the activating ligands MICA, MICB, or ULBP2 early during infection, thereby creating a window of opportunity for NK cell recognition." (PMID 24787765, 2014). "In particular, CMVs avoid expression of stress‐ or infection‐induced ligands for activating NK cell receptors on the surface of infected cells, especially the ligands ULBP1, ULBP2, MICA, and MICB for the human activating NKG2D receptor." (PMID 39931744, 2025). "Due to the deletion of the UL16 ORF in the ULBP2‐expressing mutants, induction of other NKG2D‐L was expected upon infection, and, hence, slightly increased ULBP1 expression was observed in HFF infected with ULBP2‐W and ULBP2‐S variants." (PMID 39931744, 2025). "We demonstrate that the infected cells respond to the infection and that, upon infection, the mRNA and the total protein amount of MICA, MICB, ULBP2, and ULBP3 are upregulated." (PMID 32698530, 2020). "Twenty-four hours following infection, we stained the mock-infected and the infected cells for the expression of NKG2D ligands: MICA, MICB, ULBP1, ULBP2, ULBP3, and ULBP4." (PMID 32698530, 2020). "While ULBP-1, ULBP-2/5/6, and ULBP-3 are rarely expressed on healthy primary CD4+ T cells, it is well established that infection with several laboratory strains of HIV can induce their surface expression." (PMID 29023371, 2017). "In contrast, at 72 hours post infection, the mRNA levels of ULBP1 were substantially reduced, while the ULBP2 and ULBP3 mRNA levels remained unchanged." (PMID 26992229, 2016). "We confirmed that infection of HepG2-NTCP with HBV cells substantially increased the expression of ULBP1 and ULBP2 mRNA in co-cultured THP-1 macrophages, which was cultured using transwell co-culture system." (PMID 27630638, 2016). "ULBP2 and ULBP3 were downregulated at earlier stages of infection." (PMID 37753084, 2023). "Intracellular protein levels of MICA, MICB, ULBP2, and ULBP3 were tested 48 hrs post-infection." (PMID 37753084, 2023). "MICA, MICB, ULBP2, and ULBP3 were upregulated following infection with both HMPV/WT and HMPV/ΔG." (PMID 32698530, 2020). "While infection with a UL16 deletion mutant caused the expected increase in MICB and ULBP2 cell surface expression, deletion of UL142 did not have a similar impact on its target, MICA." (PMID 24787765, 2014). "MICA and ULBP2 expression were not affected following infection." (PMID 34721381, 2021). "As the block deletion mutants were made on a ΔUL16ΔUL18 background, the parental HCMV control up regulated MICB and ULBP2 relative to mock-infected cells, whereas the ΔUS18–22 mutant up regulated cell surface levels of MICA relative to both mock- and parental HCMV-infections." (PMID 24787765, 2014).
infection (continued). "Shedding of MICA, ULBP2, and ULBP3 was not enhanced post-infection, whereas shedding of MICB was reduced." (PMID 37753084, 2023).
blood cancers (1 paper, 2023). "Notably, upregulated genes in short survival cases across solid and blood cancer cohorts include a common immune gene signature comprising MAGEC2, SSX1 and ULBP2." (PMID 36649303, 2023). "Three upregulated genes were common to both solid and blood cancers (MAGEC2, SSX1, ULBP2), but there were no common downregulated genes." (PMID 36649303, 2023).
ULBP2 also shares sentences with these, for which no sentence is quoted: chronic myelogenous leukemia (2 papers); adenocarcinoma (1); allergic asthma (1); Allergy (1); asthma (1); cervical (1); cervical intraepithelial neoplasia (1); hematopoietic cancers (1); immune diseases (1); invasive breast carcinoma (1); latent infection (1); lung squamous cell carcinoma (1); lymphoma (1); multiple myeloma (1); Osteochondrosis (1); ovarian tumors (1); pancreatitis (1); prostate carcinoma (1); renal carcinoma (1); thyroid (1); tonsil (1).